ENSG00000288564 (novel protein)
Gene: Protein-coding gene on chromosome 6 (43,051,066 to 43,058,185, reverse strand). Ensembl gene ENSG00000288564.
Genetic constraint (gnomAD): Missense variants: 303 observed, 340.79 expected, observed/expected ratio (o/e) 0.89, 90% interval 0.81 to 0.98. Synonymous variants: 102 observed, 120.91 expected, observed/expected ratio (o/e) 0.84, 90% interval 0.72 to 0.99.